HIF1A (hypoxia inducible factor 1 subunit alpha)
Diseases named in the same sentence as HIF1A in open-access papers (continued):
Sharing a sentence is not in itself a finding about the gene and the disease.
colitis (continued). "Consistent with the improved colitis clinical symptoms, GTA treatment decreased the number of infiltrating T cells and macrophages in the colon and increased the number of IgA+ B cells and IgA+ plasma cells as well as the secretion of IgA in the stool of Hif1a cKO mice." (PMID 39543372, 2025). "However, studies on the role of hypoxia/HIF-1α or SCFAs in IBD present contradictory conclusions, possibly related to factors such as colitis models, SCFA types and concentrations, gut environment (hypoxia levels, pH), and cell phenotype heterogeneity during experimentation." (PMID 38605960, 2024). "Another recent study demonstrated that in a mouse model of dextran sulfate sodium (DSS) induced colitis, the absence of dendritic HIF-1α results in enhanced severity of intestinal inflammation via increased production of pro-inflammatory cytokines IL-6 and IL-23." (PMID 34571989, 2021). "To investigate whether local HIF-1α stabilization by CG-598 could protect against intestinal inflammatory insult, we used two animal models including DNBS-induced and DSS-induced colitis representing experimental murine models for Crohn’s disease and ulcerative colitis, respectively." (PMID 33519819, 2020). "However, HIF-2α-KO (but not HIF-1α-KO) Treg cells are functionally defective in suppressing effector T cell-induced colitis and inhibiting airway hypersensitivity." (PMID 33024109, 2020). "The HIF-1α isoform is beneficial to repression of oxazolone- and 2,4,6-trinitrobenzene sulfonic acid (TNBS)-induced colitis via induction of barrier-protective genes whereas HIF-2α is detrimental to dextran sulfate sodium (DSS)-induced colitis via increased inflammatory responses." (PMID 33519819, 2020). "Thus, we also explored the relationship between HIF-1α and TFF-3 in DSS-induced colitis." (PMID 32713852, 2020). "Moreover, absence of intestinal epithelial Hif1-α markedly changed the population of IELs in NSAID-induced small intestinal injury and increased susceptibility to dextran sulfate sodium-induced colitis." (PMID 31040849, 2019). "The mucosal expression of mRNA for TNF-α, IL-1β, iNOS, COX-2, SOD-1, SOD-2, GPx mRNAs, and the hypoxia inducible factor (HIF)-1α protein expression were upregulated in colonic mucosa of treadmill exercising HFD mice with colitis compared with those without exercise." (PMID 31117199, 2019). "Since we could not detect upregulation of Hif1α signaling in the course of the colitis starvation-refed group, regulation of NDRG3 gene expression in the colon needs further investigation." (PMID 28955126, 2017). "The Tregs without HIF-1α could not control T cell-mediated colitis." (PMID 37201028, 2023). "Notably, HIF-1α and HIF-2α can oppose each other during intestinal inflammation: for example, epithelial cell HIF-1α helps maintain intestinal barrier functions during colitis, whereas HIF-2α worsens colitis by promoting tumor necrosis factor alpha (TNFα) production in epithelial cells." (PMID 30455703, 2018). "Lastly, the temporal regulation of HIF-1α and HIF-2α has not been critically assessed in chronic models of colitis." (PMID 26812949, 2016). "Thus, a myeloid double knockout of HIF-1α and HIF-2α compensated for the effects observed with a single knockout and showed no change in the clinical course of colitis compared to mice with both HIFs intact." (PMID 33202783, 2020). "Therefore, the results collectively indicate that hMRP8 Hif-1a KO mice, but not hMRP8 Hif-2a KO mice, were protected from DSS-induced colitis." (PMID 29967068, 2018). "In both studies, dendritic cells lacking HIF-1α were the more potent inducers of an inflammatory response—with benefits for the outcome in Leishmania infection but abundant inflammation and more severe illness in DSS colitis." (PMID 26966693, 2016).
Cerebral ischemia (138 papers, 2012 to 2026). Restriction of arterial blood supply to the brain associated with insufficient oxygenation to support the metabolic requirements of the tissue. "The suppression of HIF-1α was reported to reduce microglia-associated inflammation after brain ischemia." (PMID 38287411, 2024). "One of the mechanisms to counter cerebral ischemia and hypoxia is the activation of the hypoxia-induced factor-1α (HIF-1α) and HIF-1α-dependent genes encoding proteins that promote the adaptation of brain cells to hypoxia." (PMID 36834685, 2023). "•FoxO3a agonist trifluoperazine reduced ferroptosis-associated cerebral ischemia/reperfusion(CIR) injury in rats through AMPK/FoxO3a/HIF-1α signaling and mitochondria-dependent mechanisms." (PMID 37267686, 2023). "The HIF-1α/VEGF signaling pathway reduces apoptosis caused by cerebral ischemia/reperfusion by regulating cell metabolism, angiogenesis, and cell death to cellular adaptation to hypoxia." (PMID 36909178, 2023). "We identified the FoxO3a activator trifluoperazine (TFP), a FDA-approved antipsychotic agent that reduced ferroptosis-associated brain ischemia/reperfusion (CIR) injury in rats through AMPK/FoxO3a/HIF-1α/SLC7A11 signaling and mitochondria-dependent mechanisms." (PMID 37267686, 2023). "Cerebral ischemia is associated with increased expression of sirtuin in infiltrating Tregs, and this is mediated by the transcription factor, hypoxia-inducible factor 1-alpha (HIF-1α), which can be modulated to expand Treg numbers." (PMID 32477327, 2020). "Cobalt chloride (CoCl2) induces chemical hypoxia through activation of hypoxia inducible factor-1 alpha (HIF-1α), which is a key pathogenic factor in cerebral ischemia in vivo." (PMID 30594149, 2018). "LRIP exhibits a protective effect against cerebral ischemia/reperfusion and the possible mechanism is associated with the suppression of HIF-1α in stroke rats." (PMID 26715469, 2015). "Although Hif-1α has been implicated as an important player in cerebral ischemia, its function in cerebral ischemic condition is still unclear." (PMID 26030758, 2015). "Previous studies also confirmed the “biphasic activation” phenomenon of HIF-1α after cerebral ischemia, which may cause dual effects of protection of and damage to neurons." (PMID 34483819, 2021). "Cerebral ischemia in rat brains caused a time-dependent increase in HIF-1α and PACAP38 expression." (PMID 25523790, 2015). "Therefore, we deduced that LRIP in MCAO rat model should be an effective method for the treatment of brain ischemia and the molecular events were possibly associated with the downregulation of HIF-1α expression." (PMID 26715469, 2015). "In some models, HIF-1α stabilization has been shown to promote recovery of spinal cord injury, cerebral ischemia (60, –62), and TBI." (PMID 41481451, 2026). "In summary, HIF‐1α/VEGF/Notch1 levels increase following cerebral ischemia but decrease after treatment." (PMID 40019048, 2025). "To further investigate the mechanism of combined AS and TMP improving cerebral ischemia, we detected the mRNA and protein expression of HIF-1α and VEGF in the infarcted cortex based on the network pharmacology results." (PMID 40869300, 2025). "Some studies indicate that activating the HIF‐1α/VEGF/Notch1 pathway during cerebral ischemia treatment can promote angiogenesis and restore blood flow." (PMID 40019048, 2025). "Recent findings suggest that lactate can elicit neuroprotective responses via the activation of HIF-1α, which surprisingly suppresses the NF-κB pathway in cerebral ischemia." (PMID 41288829, 2025). "By altering the microglial response, inhibition of HIF-1α has been demonstrated to decrease infarct volume and improve neurological recovery in models of cerebral ischemia." (PMID 41288829, 2025).
Cerebral ischemia (continued). "Dexmedetomidine (Dex) demonstrates neuroprotective properties by modulating the HIF-1α pathway, as evidenced by its ability to reduce neuronal apoptosis and ameliorate cerebral ischemia-reperfusion injury in animal models." (PMID 41431031, 2025). "On the contrary, a recent study has reported that the STAT3/HIF-1α/PTRF axis exacerbates cerebral ischemia/reperfusion (I/R) injury." (PMID 40653468, 2025). "Neuronal STAT3/HIF-1α/PTRF axis-mediated bioenergetics can exacerbate cerebral ischemia–reperfusion injury via PLA2G4A55." (PMID 38360841, 2024). "Hypoxia-inducible factor-1α (HIF-1α) is an oxygen-sensitive transcription factor that plays a crucial role in regulating and mediating adaptative metabolic responses to hypoxia and cerebral ischemia." (PMID 39108657, 2024). "Tissue hypoxia and cerebral ischemia activate HIF-1α, which in turn activates transcription of the EPO and Vascular Endothelial Growth Factor (VEGF) genes." (PMID 38302546, 2024). "Another factor that is known to induce revascularization in the ischemic lesions of cerebral ischemia is hypoxia-inducible factor 1α (HIF1α)." (PMID 39305405, 2024). "Cardamonin has significant anticancer, anti-inflammatory, and antioxidant activities and neuroprotective effects and can attenuate cerebral ischemia/reperfusion injury through activation of the HIF-1α/VEGFA pathway." (PMID 39359632, 2024). "It is evident that HIF‐1α is mainly expressed in neurons and exerts neuroprotection against cerebral ischemia." (PMID 39072998, 2024). "HIF-1α plays a vital role in the development of cerebral ischemia by participating in numerous processes, including metabolism, proliferation, and angiogenesis." (PMID 38791263, 2024). "SMJF Granule promoted angiogenesis through HIF-1α pathway, thereby alleviating cerebral ischemia injury." (PMID 38600597, 2024). "Endogenous substances, including amino acids and neurotransmitters, have a neuroprotective role against cerebral ischemia by controlling HIF-1α." (PMID 38790642, 2024). "In periods of cerebral ischemia, HIF-1α is activated due to insufficient oxygen supply and a decrease in the partial pressure of oxygen in the tissues." (PMID 36998597, 2023). "It was found that in response to the cerebral ischemia formation, HIF-1a is expressed, which initiates the launch of compensatory mechanisms for energy production." (PMID 37138769, 2023). "VEGF is a renowned downstream target gene of HIF-1α and widely involved in the pathological process of cerebral ischemia, and the VEGF family is distinguished by its powerful angiogenic properties." (PMID 36998597, 2023). "HIF-1α promotes cystine-glutamate antiporter (SLC7A11/xCT) expression which contributes to cerebral ischemia-reperfusion (CIR)-mediated glutamate release and excitotoxicity." (PMID 37267686, 2023). "At the same time, the study also found that HIF-1α is expressed in the chronic hypoxic zone surrounding the infarcted area during cerebral ischemia." (PMID 36998597, 2023). "Neuron-specific inactivation of the HIF-1α increases brain injury in a mouse model of transient focal cerebral ischemia." (PMID 37296633, 2023). "Meanwhile, HIF‐1α has also been regarded to be an important factor modulating apoptosis after brain injuries, such as cerebral ischemia and traumatic brain injury." (PMID 37600117, 2023). "It has been shown that an increase in the expression levels of HIF-1α exerts a neuroprotective activity in cerebral ischemia, hypoxia injury and TBI." (PMID 35810304, 2022). "In situations of hypoxia and cerebral ischemia, there is a self-protective mechanism mediated by an increase in the expression of HIF-1α that allows the brain to increase the tolerance to hypoxia through transcriptional and post-transcriptional mechanisms." (PMID 35810304, 2022). "Hypoxia activates astrocytes to secrete hypoxia‐inducible factor 1α (HIF‐1α), the core regulator of angiogenesis in the repair phase of cerebral ischemia." (PMID 35855611, 2022).
Cerebral ischemia (continued). "Conflicting reports have aroused many debates on the certain role of HIF-1α in rats after cerebral ischemia." (PMID 35449809, 2022). "Previous studies have shown that HIF-1α mediates angiogenesis after cerebral ischemia and rescues ischemic penumbra of brain tissue by promoting the expression of its target gene, VEGF." (PMID 35449809, 2022). "Combined with previous studies, how celastrol alleviates cerebral ischemia-reperfusion injury via HIF-1α need further study." (PMID 35677353, 2022). "While HIF-1α was found to be an essential participator in cerebral ischemia, its potential role and its target genes in tissue injury after cerebral ischemia remain controversial." (PMID 35449809, 2022). "Although the role of HIF-1α in cerebral ischemia remains complex, the role of HIF-1α as mediator of BSc2118-induced neuroprotection is appealing based on the data present." (PMID 35462700, 2022). "The novel proteasome inhibitor BSc2118 protects against cerebral ischemia through HIF1A accumulation and enhanced angioneurogenesis." (PMID 35462700, 2022). "In the early stage of cerebral ischemia, hypoxia-inducible factor 1α (HIF-1α) and Sp1 transcription factor (Sp1) induce the upregulation of APJ expression." (PMID 35668778, 2022). "And it has neuroprotective effects by inhibiting HIF-1α/LDHA-mediated inflammatory response after cerebral ischemia/reperfusion injury." (PMID 36467061, 2022). "HIF-1α is a transcription factor that can be expressed rapidly in response to hypoxia during brain ischemia." (PMID 36012320, 2022). "Upregulation of iNOS is triggered by several stimuli, including proinflammatory mediators, and transcriptional factors (e.g., NF-kB or HIF-1a) which are activated during brain ischemia." (PMID 36555816, 2022). "HIF-1α was an important regulatory node in reducing oxidative stress and inflammation in stroke and was activated after cerebral ischemia." (PMID 34336097, 2021). "Taken together, the current results demonstrated that GHI has protective effects against cerebral ischemia via the PKC/HIF-1α signal pathway." (PMID 34539402, 2021). "VEGF, a well-known downstream target gene of HIF-1α, is extensively involved in the pathological processes of cerebral ischemia." (PMID 34966392, 2021). "This indicates the importance of HIF-1α activation as an efficient strategy to mitigate the inflammatory response following cerebral ischemia." (PMID 34205911, 2021). "Inhibition of immunoproteasome LMP2 promotes angiogenesis and enhances HIF-1α accumulation in a rat model of cerebral ischemia, supporting the conclusion that the immunoproteasome possesses proteolytic activity involved in protein degradation." (PMID 34857032, 2021). "Other hypoxia-mediated signaling pathways related to HIF-1α have been identified to have a neuroprotective role after cerebral ischemia." (PMID 34966392, 2021). "Previous studies have indicated that HIF-1α inhibits neuronal apoptosis following cerebral ischemia in rats by upregulating EPO." (PMID 34288817, 2021). "Glycine reduces neuroinflammation in rats with cerebral ischemia by downregulating NF-κB p65, thereby decreasing the expression of HIF-1α and ameliorating microglial polarization." (PMID 34966392, 2021). "In conclusion, the present study demonstrated that ADPN treatment is effective in attenuation of cerebral ischemia-reperfusion injury, and HIF-1α-regulated antioxidant response is the main molecular mechanism responsible for ADPN treatment for stroke." (PMID 34336097, 2021). "A recombinant adenovirus engineered to express HIF-1α demonstrated that HIF-1α attenuated neuronal apoptosis partially through upregulating EPO following cerebral ischemia in a rat model." (PMID 34912224, 2021). "In this study, we investigated the curative effect of GHI on cerebral ischemia–reperfusion (I/R) injury via the PKC/HIF-1α pathway in rats." (PMID 34539402, 2021).
Cerebral ischemia (continued). "Among them, s-nitrosylation and HIF-1α stabilization seem to be of importance in pathophysiology of brain ischemia." (PMID 34439764, 2021). "The novel proteasome inhibitor BSc2118 enhances angioneurogenesis and protects against cerebral ischemia-induced damage, which is via HIF-1α accumulation." (PMID 32089771, 2020). "DEX protects against cerebral ischemia via inhibition of neuronal autophagy by upregulation of HIF-1α." (PMID 33132849, 2020). "Proteasomal inhibition confers neuroprotection against cerebral ischemia through HIF-1α stabilization." (PMID 32089771, 2020). "Taken together, these findings reveal that hypoxia-preconditioned OM-MSC inhibits pyroptotic and apoptotic death of microglial cell in response to cerebral ischemia/reperfusion insult by activating HIF-1α in vitro." (PMID 32507769, 2020). "Taken together, these findings revealed that hypoxia-preconditioned OM-MSCs attenuated apoptosis or pyroptosis in BV2 microglial cells under cerebral ischemia/reperfusion conditions by regulating the expression levels of HIF-1α in vitro." (PMID 32507769, 2020). "Administration of 2-Methoxyestradiol, an inhibitor of Hif1α, has been shown to provide neuro-protection against cerebral ischemia and traumatic brain injury in animal models." (PMID 29701696, 2018). "Biphasic expression pattern of HIF-1α was observed in some of the studies following in vitro and in vivo models of cerebral ischemia." (PMID 30671433, 2018). "Inhibition of HIF-1α in the early stages of neonatal cerebral ischemia with vitexin conferred neuroprotection in vivo." (PMID 30671433, 2018). "Inhibition of the 20S proteasomal activity can protects HIF-1α from degradation and provides neuroprotection in cerebral ischemia." (PMID 28979191, 2017). "Understanding cell-type dependent effects of HIF-1α will undoubtedly shed new lights on its role in cerebral ischemia and thus provides potential approaches to augment its beneficial effect and reduce its detrimental function." (PMID 28855859, 2017). "Using in vitro ischemic model (oxygen and glucose deprivation) and a mouse model of middle cerebral artery occlusion, we tested effects of inhibitors of proteasomes and prolyl hydroxylase (PHD) on HIF-1α stability and brain injury in cerebral ischemia." (PMID 28566998, 2017). "Our data showed that β2-adrenergic receptor inhibition attenuated HIF-1α upregulation as well as BBB damage within the first several hours of cerebral ischemia." (PMID 28855859, 2017). "In summary, BBB damage is reduced by blockade of β2-adrenergic receptor-mediated HIF-1α upregulation during acute cerebral ischemia." (PMID 28855859, 2017). "Taken together, blockade of β2-AR-mediated HIF-1α upregulation mediates BBB damage during acute cerebral ischemia." (PMID 28855859, 2017). "In other words, brain ischemia enhances HIF-1α and quickly produces large amounts of ROS, and the subsequent reactions cause cell and brain damage." (PMID 28865453, 2017). "HIF-1α is also involved in angiogenesis, cell survival, anaerobic metabolism, cell migration, and differentiation, suggesting that HIF-1α plays an important role in the functional recovery of cerebral ischemia." (PMID 27517324, 2016). "Recently, one study showed that HIF-1α-induced VEGF overexpression in BMSCs protected neuron against brain ischemia." (PMID 27517324, 2016). "Cerebral ischemia increased the expression of activated nuclear HIF-1α, which was inhibited by 2-ME2 (100 mg/kg) injection." (PMID 25523790, 2015). "Although several miRNAs have been reported to target HIF-1α, these were mostly done in cancer cells and hence the interaction of miRNAs and Hif-1α in cerebral ischemia is still poorly understood." (PMID 26030758, 2015). "We verified the expression of Angpt2, Bnip3, Mmp9, Pai1 and Vegfa genes since they were reported to be regulated by HIF-1α during cerebral ischemia." (PMID 26030758, 2015).